CD44 (CD44 molecule (IN blood group))
Diseases named in the same sentence as CD44 in open-access papers (continued):
Sharing a sentence is not in itself a finding about the gene and the disease.
melanoma (continued). "JQ1 was characterized by induction of inhibitory relationship linking regulators of inflammation (IFNG, IL17A, TGFB2), melanoma biological behavior (EGFR, WNT3A, TEADs, MRTFB), cell-cell interaction (CD44, CCN2), YAP pathway (LLGL2, NSUN6) and main transcriptional regulators (FOS, JUN, FOXM1)." (PMID 36397155, 2022). "TGF-β-expressing B cells in the melanoma tumor microenvironment assembled in clusters and interacted with T cells via lymphoid recruitment (SELL, CXCL13, CCL4, CD74) signals and with Tregs via CD47:SIRP-γ, and FOXP3-promoting Galectin-9:CD44." (PMID 35909944, 2022). "In melanoma, Jobani had revealed that combination therapy together with allicin and ATRA (all-trans-retinoic acid) significantly decreased the IC50 (half-maximal inhibitory concentration) value obtained for ATRA alone in CD44+ melanoma cells." (PMID 35956766, 2022). "Similarly, we found a significant positive association between HIF1α and SOX2 (R = 0.49, p-value = 0.0089) along with CD44 and SOX2 (R = 0.39, p-value = 0.045) in melanoma cancers." (PMID 35186918, 2022). "CD44/E-selectin-binding signaling upregulates intercellular adhesion molecule 1 (ICAM-1) expression on the cell surface via the PKCα/p38/Sp1 pathway, thereby promoting melanoma cell metastasis." (PMID 35936713, 2022). "Finally, analysis of archival melanoma patient samples confirmed a vice versa relationship of NRF2 and CD44 expression." (PMID 34951143, 2022). "In human melanoma cells, constitutive shedding of CD44 was reported to be mediated by ADAM10 but not by MT1-MMP or ADAM17 despite all of these enzymes were expressed in the cells." (PMID 34796172, 2021). "Conversely, the non-kinase mediated pathways are likewise important in melanoma cells progression, such the non-kinase membrane glycoprotein CD44 activation." (PMID 33440679, 2021). "Melanoma model in zebrafish has confirmed that THOR-IGF2BP1 interaction promotes melanoma development and progression by stabilizing several oncogenes such as IGF2 and CD44." (PMID 34638331, 2021). "In this study, HA-targeted liposomes bound to the CD44+o-overexpressing B16F10 murine melanoma cell line but not to the CV-1 African green monkey kidney cell line, which expressed low levels of CD44." (PMID 34944493, 2021). "Moreover, we further demonstrated that low levels of RNF128 activated canonical Wnt signaling and participated in a positive feedback for the CD44-Wnt loop; thus, RNF128 functions as a tumor suppressor gene in melanoma." (PMID 30832692, 2019). "Next we determined whether CD44, the principal cell surface receptor for HA, plays a role in the ability of HA to stimulate BMP-induced Id1 and Id3 expression in B16-F10 and Ret melanoma cells." (PMID 30297743, 2018). "In most patients, melanoma cells exhibited ErbB3/Her3, CD44/Pgp-1, ICAM-1/CD54 and IGF-1-R/CD221, but did not express CD20, ErbB2/Her2, KIT/CD117, AC133/CD133 or MDR-1/CD243." (PMID 24489649, 2014). "The stromal coverage of CD44 was only 6-25% in average in LN metastases, but it was not significantly different than in deep melanomas." (PMID 23560496, 2013). "In stroma, the coverage of CD44 staining was high (76-100% in average) in benign and dysplastic nevi, in situ melanomas and superficial melanomas and was not statistically different among these groups." (PMID 23560496, 2013). "Versus CD44+ melanoma cells, those lacking CD44 bound less toxin and were dose-dependently resistant to C. perfringens iota, as well as Clostridium difficile and Clostridium spiroforme iota-like, toxins." (PMID 23236484, 2012). "Mouse melanoma B16-F10 cells also contain CSC-like cells, which express CD133, CD44, and CD24." (PMID 20950440, 2010). "However, the expression of CD24, CD44 and CD133 (or ABCB5) in melanoma B16 cells implies that CSC-like cells emerge during tumorigenesis." (PMID 20950440, 2010).
melanoma (continued). "Interestingly, B16-F1 and B16-F10 cells induced expression of CD133, ABCB5, CD44 and CD24, which are expressed in mouse melanoma CSC-like cells during tumorigenesis, and ectopic generation of GDF3 increased the CD24 expression." (PMID 20950440, 2010). "Additionally, CD44 was readily detected in melanoma exosomes but conspicuously absent from those originating from normal melanocytes, reinforcing the tumor-specificity of exosomal biomarker profiles." (PMID 40805206, 2025). "Accordingly, the CD44 kd did not impair but rather improved the adhesive properties of HT‐29 cells (E‐selectin binding, SLeA expression), contrasting our previous observations with melanoma and osteosarcoma cells." (PMID 37849446, 2024). "Moreover, to gain additional insight into the potential role and relevance of IFN-α against CSC-melanoma-markers, CD133, p75 and CD44 markers were analyzed; however, we were able to detect only CD44 expression, which was significantly reduced in exosomes obtained from IFN-α-treated spheres." (PMID 37509327, 2023). "EVs from the melanoma cells did not change the expression of CD44, another cancer stem cell marker and EMT inducer; however, this protein is indispensable for proliferation and differentiation of the keratinocytes, so it is strongly activated in this type of cells." (PMID 35327461, 2022). "Due to that, we observed lower standard deviation and, thus, statistically significant differences in the level of MMP2, MMP14, RUNX2, or CD44 in CAFs obtained by incubation with conditioned media, but not by co-culturing with melanoma cells present on Transwell inserts." (PMID 35538545, 2022). "Thus, down‐regulation of NRF2 not only induces CD44, but maybe also MITF, and both markers confer anti‐cytotoxic abilities to melanoma cells." (PMID 34951143, 2022). "Given that the CD44/HA axis promotes BMP signalling in chondrocytes, and the correlation between these factors and poor prognosis in melanoma, we hypothesized that HA might promote BMP4/7-dependent Id1/3 protein expression in melanoma cells in CD44-dependent manner." (PMID 30297743, 2018). "Additionally, overexpression of miR-200c in CD44+CD133+ CSCs resulted in downregulation of Zeb1 expression, reduction in cell proliferation, colony formation, cell migration and invasion as well as tumorigenic potential in melanoma." (PMID 28137308, 2017). "Moreover, all melanoma cell lines expressed as mRNA other markers of cancer stem cells, such as CD44, ALDH1 and Nodal (data not shown)." (PMID 26460958, 2015). "ZEB1 downregulation in B16-F10 melanoma cells and in its presumed cancer-stem cell CD133+ CD44+ subpopulation reduced their tumor growth in vivo, yet it has not been shown whether lack of ZEB1 effectively depletes the CD133+ CD44+ fraction in B16-F10 tumors as such." (PMID 25538895, 2014). "We could not establish that the sensitivity of individual melanoma cell lines to MIF depletion resulted from the differential expression of known MIF receptors (i.e. CD74/CD44 and/or CXCR4)." (PMID 25168062, 2014). "However, our real-time PCR measurements suggest that quantitatively, melanoma is not a uniform group and CD44 variable exon expression levels can follow different patterns." (PMID 23342032, 2013). "However, free DOX was not as efficacious as CD44 targeted liposome encapsulated DOX towards M14#5 melanoma cells." (PMID 23213537, 2012). "Similarly, albumin nanoparticles functionalized with HA to specifically target CD44-overexpressing cells and filled with all-trans retinoic acid (HA-eNPs/ATRA) were found to suppress the tumorigenicity as well as the metastatic potential of CD44-enriched melanoma cells." (PMID 39199632, 2024). "For instance, as few as 100 CSCs (isolated and identified as CD44+ CD24-) were able to induce tumor growth in non-obese diabetic/severe combined immuno-deficient (NOD/SCID) mice, while in a humanized mouse model (NSGTM), injection of 1000 melanoma CD71+ cells resulted in successful tumor induction." (PMID 33202648, 2020).
melanoma (continued). "In addition, cordycepin was able to decrease the expression of MMP-2, MMP-9 and CD44 and suppress cell motility, suggesting that cordycepin not only regulates early stages of melanoma metastasis, but also late stages of melanoma dissemination, such as adhesion and extravasation." (PMID 25868853, 2015). "Since CD44, as a cell surface glycoprotein, plays an important role in cell-matrix interaction, it was important to examine whether different matrix components change the alternative splicing pattern, or whether the ASP is stable and possibly inherent to melanoma-specific behavior." (PMID 23342032, 2013). "Interestingly,statistical analyses revealed that in primary melanoma, simultaneousexpression occurs more frequently when compared to the metastaticmodels (88% vs 60%) but any specific correlation was not identifiedamong tested subgroups including CD44 + vimentin, CD44 + MCAM, andvimentin + MCAM." (PMID 40621031, 2025). "We also tested the modulators of the EMT pathway (spectralflow cytometry of vimentin and MCAM and CD44 expression) to figureout differences between BRAF and non-BRAF positive melanoma cell linesusing large tumorspheres." (PMID 40621031, 2025). "Similar observation were determined in four CTC-positive melanoma-BM patients; most CTCs showed a strong expression of CD74 (15/26) and CD44 (19/26), with only one patient not showing any expression of either protein." (PMID 34209696, 2021). "There exists so far no information about their affinity to the CD44 3’ UTR in general and in particular for melanoma cells." (PMID 31741714, 2019). "CD44 levels are elevated in multiple cancer types and MCAM is expressed in melanoma cells and not untransformed melanocytes." (PMID 29648538, 2018). "The CD44-targeted DOX-loaded PEG liposomes and nontargeted DOX loaded PEG liposomes were tested in a B16F10 mouse melanoma model." (PMID 23213537, 2012). "The CD44 expression correlated to PD-L1, but not to MART-1 expression in malignant melanoma." (PMID 31741714, 2019). "Interestingly, the repeat of the experiment with mesenchymal melanoma cell line MDA-MB-435 with predominant expression of the standard CD44 isoform 4 did not lead to the same results, overall expression of CD44 was significantly downregulated." (PMID 38106992, 2023). "Therefore, blocking coalescence with the anti-CD44 mAb H4C4 may not be due to an interaction with hyaluronic acid, unless the interaction is autocrine in nature–i.e., the melanoma cells secrete the hyaluronic acid with which they then interact." (PMID 28264026, 2017).
breast tumors (218 papers, 2008 to 2026). "The CD44+ genotype in primary breast tumors and metastasis has been positively associated with tumor initiation and progression, metastasis and increased stemness, whereas CD44+/CD24- is considered a hallmark of BC stem cells." (PMID 37298091, 2023). "In fact, primary breast tumour cells with a CD44+CD24− profile were associated with increased metastatic capacity and poor survival probability." (PMID 35326385, 2022). "BRCA1-associated murine breast tumors consist of CD44+/CD24− and CD133+ cells with bCSC-like features, showing a greater intrinsic colony-forming potential that can regenerate breast tumors in NOD/SCID mice." (PMID 35392236, 2022). "The number of cases expressing CD44 variants was significantly different between the breast tumour tissues and the normal tissues surrounding the tumours (χ2 = 10.8, p = 0.001)." (PMID 33210459, 2021). "The interaction of CD44 with histone-associated genes upregulated NF-κB activity and chemoresistance in breast tumor cells." (PMID 34445612, 2021). "Breast tumor stem cells appeared to have low levels of Spinophilin mRNA, and Spinophilin loss correlated with increased stem-like cell appearance in breast tumors, as indicated by an increase in CD44+/CD24- cells." (PMID 29285244, 2017). "A recent report indicated that a new HA/CD44-mediated signaling mechanism is involved in the regulation of Twist-associated miR-10b production and breast tumor cell invasion." (PMID 27070574, 2016). "A recent study on 35 breast tumors of the luminal subtype showed that CD44(+) CD24(-/low) tumors were significantly associated with axillary lymph node metastasis compared with those of CD44(+) CD24(+) type." (PMID 24392029, 2013). "Expression of the hyaluronan (HA) receptor CD44 associated with the basal-like subgroup in a cohort of 141 breast tumor specimens (P = 0.018)." (PMID 22621373, 2012). "Notably, this isoform switch from CD44 variant isoforms to isoform 4 was essential for forming breast tumors in mice." (PMID 38106992, 2023). "Furthermore, CD44+/CD24low/- cells are more frequent in basal breast tumors (and particularly high in BRCA1 mutated tumors) suggesting that the cancer stem cells are not restricted to those markers." (PMID 24124614, 2013). "Future in vitro studies with RGD-free HAGM cryogel-based tumor models could further elucidate the role of HA-mediated CD44 activation in breast tumor progression and metastasis and could investigate the specific variant of CD44 isoforms involved in CD44/HA-mediated signaling pathways." (PMID 35198956, 2022). "Incidentally, transcriptional co-activators YAP/TAZ were found to be upregulated in CD44+/CD24-/ALDH+ cells isolated from patient breast tumors and CSC-enriched mammospheres." (PMID 39979255, 2025). "YAP/TAZ was also found to interact with DRP1 in the cytoplasm, with this interaction being exclusive to the CD44+/CD24− cell population isolated from patient breast tumors." (PMID 39979255, 2025). "Breast CSCs (BCSCs) represent a small subset of cells that contain stem cells in breast tumors, characterized by the CD44+/CD24 expression profile." (PMID 38255288, 2024). "KYNU has been identified as a novel transcriptional target of CD44-downstream signaling and underpins CD44-promoted breast tumor cell invasion." (PMID 38962317, 2024). "In this study, the overexpression of CD-44 was found in breast tumour cells, confirming its potential significance in cancer biology." (PMID 38172135, 2024). "In 3D scaffolds with the same stiffness as breast tumor tissue, stemness markers (Nanog, Sox2, and Oct4) and CD44 were found to be expressed at a higher level than in 2D cultures." (PMID 37468874, 2023). "Disruption of the interaction between HA and CD44 in breast tumour cells has been shown to inhibit PKC-Nanog signalling mediated miR-21 production and suppress cell survival." (PMID 37707669, 2023).
breast tumors (continued). "Huang and colleagues have found that miR-520c and miR-373 suppress CD44 and induce in vitro and in vivo cell invasion and migration in breast tumor cell line." (PMID 37070617, 2023). "This pattern is suggestive of increased cancer stemness and is consistent with earlier reports of elevated CD44 levels in high NOS2-expressing ER- breast tumors." (PMID 37169743, 2023). "Comparing different breast tumor cell systems of EMT, we thus first report here an association between CD44 and TF expression in EMT+ cellular backgrounds." (PMID 35805061, 2022). "For example, breast tumors expressing CD44+/CD24low have been shown to exhibit enhanced invasion and metastasis." (PMID 35892853, 2022). "In our study, we identified a mechanism of TF regulation by CD44 in breast tumor cells which modulates their procoagulant activity." (PMID 35805061, 2022). "In support of our results, Nam and colleagues similarly reported a strong decreased expression of Sp1 after CD44 silencing in MDA-MB-231 and Hs578T breast tumor cells, that was associated with decreased migratory/invasive properties." (PMID 35805061, 2022). "CD44 is a multifunctional class I transmembrane glycoprotein and is widely used as a marker of breast tumor-initiating cells, especially in TNBC." (PMID 36193887, 2022). "Based on the microarray results we have previously validated three target genes along with their signaling pathways (Cortactin, Survivin and TGF-β2) as novel downstream target genes that underpin CD44-promoted breast tumor cell invasion." (PMID 36505828, 2022). "Overall, our results here have identified a regulatory pathway bridging CD44 to TF expression in EMT+/TF+ breast tumor cells which functionally modulate their coagulant properties." (PMID 35805061, 2022). "This fraction of breast tumor cells can form a new tumor with additional CD44+CD24−/lowLineage− bCSCs along with phenotypically different nontumorigenic cells." (PMID 35392236, 2022). "More than a co-expression of TF and CD44 in EMT+ breast tumor cells, we identify here a regulatory link between the two molecules." (PMID 35805061, 2022). "CD44+/CD24− BCSCs isolated from breast tumors, however, expressed a low level of epithelial phenotype but high levels of EMT markers." (PMID 34575017, 2021). "Claudin-low breast tumours show a significant similarity to a "tumourigenic" signature defined using CD44+/CD24− breast tumour-initiating stem cell-like cells, but the mechanism has not been fully elucidated." (PMID 34281572, 2021). "CD44 is recognized as a cancer stem cell marker in canine breast tumours, and its expression is also increased in canine leukaemia, melanoma and osteosarcoma." (PMID 33210459, 2021). "The CD44 expressed in breast tumor cells is a receptor for HA, and is attracted by HA in the tumor microenvironment during invasion of tumor cells." (PMID 34770956, 2021). "To expand our findings, we assessed HIF-1α, c-Myc, and CD44 levels in our clinic breast tumor tissues." (PMID 33469161, 2021). "Basal-like breast tumors, which display mesenchymal and invasive properties, are enriched in CD44+CD24−/low BCSCs whereas HER-2E tumors, mostly contain ALDH+ characterized by epithelial highly proliferative and metastatic BCSCs36–39." (PMID 33446633, 2021). "Transcriptional and expression levels of CD44, overexpressed in breast tumor cells, were enhanced in PCL-based cultures." (PMID 33375053, 2020). "In contrast to our results, CD44 is highly expressed in Col-I-enriched regions of human breast tumors." (PMID 32435546, 2020). "The depletion of CD44 effectively prevents aggregation, blocks lung metastasis, and impairs the ‘stemness’ of circulating breast tumor cells." (PMID 33234169, 2020). "The expression of CD44 mRNA in breast tumor cells was significantly downregulated after NAC (T = 6.387, P < 0.001)." (PMID 33282946, 2020).